MIR6718 (microRNA 6718)
Synonyms: hsa-mir-6718
Gene: MicroRNA gene on chromosome 18 (3,885,353 to 3,885,432, forward strand). Ensembl gene ENSG00000275518.
Diseases named in the same sentence as MIR6718 in open-access papers:
MIR6718 is named in the same sentence as 1 disease in open-access papers, as found by Europe PMC text mining. Sharing a sentence is not in itself a finding about the gene and the disease.
MIR6718 shares sentences with these, for which no sentence is quoted: resistant hypertension (1 paper).